IL6 (interleukin 6)
Diseases named in the same sentence as IL6 in open-access papers (continued):
Sharing a sentence is not in itself a finding about the gene and the disease.
endometritis (continued). "The data shows that the levels of TNF-α (p < 0.01), IL-6, IL-10 (68.73 ± 12.15 pg/ml), as well as acute phase proteins (SAA and Hp) in the serum of cows with subclinical endometritis were significantly higher compared to healthy cows (IL-10 53.59 ± 3.19 pg/ml) (p < 0.001)." (PMID 25846950, 2015). "An increase in the relative mRNA abundance of pro-inflammatory cytokines (IL-1β, IL-8, IL-6, and TNF-α) has also been detected in the cervical mucus of buffalo along with low intra-follicular estradiol levels, which suggests that endometritis could impede the follicular steroidogenesis." (PMID 39858163, 2025). "Hence, we concluded that ICA might express its protective effect by attenuation of the production of IL-1β, IL-6, and TNF-α as well as boosting the production of IL-10 in LPS-induced endometritis." (PMID 36142129, 2022). "Thus, this study aimed to determine gene transcription of NF‐κB subunits (RelA; NF‐κB1; NF‐κB2), proinflammatory molecules (MCP‐1; IL‐6) and hyaluronan synthases (HAS 1; HAS 2; HAS 3) in endometritis and compare them with the intensity and type of inflammatory cell infiltration." (PMID 35182075, 2022). "In the present study, the overexpression of ISG15 significantly reduced the mRNA expression levels of IL-1β, IL-6 and IL-8 in gEECs following LPS treatment, while the silencing of ISG15 had the opposite effect, indicating that ISG15 plays a protective role in goat endometritis." (PMID 34573559, 2021). "Notably, the LPS-induced tissue levels of IL-1β, IL6, and TNF-α significantly decreased with Cl-amidine treatment, indicating that inhibition of NETs formation in the process of endometritis could be advantageous in protecting uterine tissue from damage and ultimately altered endometritis." (PMID 35565576, 2022). "In mares with endometritis the serum concentrations of IL-6, PGF2α, and PGE2 were significantly higher compared with mares that did not suffer from endometritis." (PMID 34199703, 2021).
esophageal cancer (71 papers, 2012 to 2025). A primary or metastatic malignant neoplasm involving the esophagus. "Although there are few esophageal cancer data in TCGA database, the current analysis indicates that high expression of IL-6 is associated with a poor prognosis." (PMID 34881181, 2021). "To further evaluate the association of IL-6 and the anti-tumor effect of MSA on esophageal cancer, we established the 4NQO-induced esophageal tumor model in IL-6 knock-out (IL-6 KO) mice." (PMID 34393797, 2021). "Other studies found an association between IL-6 and overall survival in patients with T2 gallbladder cancer and esophageal cancer." (PMID 33920422, 2021). "Positive IL-6 staining in tissue biopsies of esophageal carcinoma were significantly associated with shorter survival, especially after RT without surgery." (PMID 30658426, 2019). "Circulating CD11b+CD14+HLA−DR− cells were found to be significantly increased in esophageal cancer and were associated with circulating IL-6 levels." (PMID 29326716, 2017). "IL-6 has been reported to be associated with disease progression and poor prognosis in patients with esophageal cancer." (PMID 26202837, 2015). "IL-6 was significantly associated with poor prognosis in patients with esophageal cancer." (PMID 23561329, 2013). "Although evidence suggests that IL-6 is a critical factor in a variety of malignancies, how IL-6 modulates the biological activities of esophageal carcinoma cells and how it is associated with the prognosis of esophageal cancer remains unclear." (PMID 23561329, 2013). "Based upon these results, we speculate that the rise in SAA may be caused by excess inflammatory cytokines, in particular IL-6, which has previously been shown to be produced by the large number of cancer cells in patients with advanced esophageal carcinoma." (PMID 22917173, 2012). "CAFs in esophageal cancer secrete IL-6, IL-8, CCL5, CXCL1, and TGF-β, leading to the activation of signaling pathways such as Akt, STAT3, ERK1/2, and NF-κB, which affect cancer cell survival, proliferation, and migration." (PMID 40136652, 2025). "And studies have shown that the secretion of interleukin 6 can facilitate the resistance of cisplatin in esophageal cancer." (PMID 40781643, 2025). "Specifically, CAFs activated by exosomal POU3F3 secrete interleukin-6, a cytokine that promotes resistance to cisplatin, a common chemotherapeutic drug for esophageal cancer." (PMID 40781643, 2025). "An interesting paper showed that Apigenin inhibited interleukin-6 (IL-6) transcription and gene expression in esophageal cancer cells and this mechanism was proposed as a promoter of apoptosis induction." (PMID 38791608, 2024). "In physiologically relevant 3D organotypic and tumoroid models as well as in mouse models of esophageal cancer, IL-6 depletion inhibited carcinogenesis." (PMID 39099925, 2024). "In summary, we demonstrated that let-7a, and its target IL-6, mediate mutual communication between radiosensitive and radioresistant esophageal cancer cells, and this cell–cell communication modulates the radiosensitivity of both cell types." (PMID 38114473, 2023). "In patients with esophageal cancer receiving surgical esophagectomy, on postoperative day 1, an increase in IL-6 and IL-8 expression was detected, which attenuated in the further postoperative course." (PMID 37568571, 2023). "Examination of patient-derived CAFs identified IL-6 as the stromal driver of therapy resistance in esophageal cancer as revealed by the two following observations." (PMID 36572816, 2023). "Another recent investigation with a total of 140 specimens of esophageal cancer clarified that CAFs regulate immunosuppressive tumor-infiltrating lymphocyte populations in the tumor microenvironment via IL-6." (PMID 36572816, 2023). "Consistent with this, correlation analysis in esophageal cancer samples showed that TRIM29 expression was negatively correlated with IL6 expression in TCGA ESCC and GSE21293 datasets." (PMID 37365152, 2023).
esophageal cancer (continued). "First, IL-6 activated the epithelial-to-mesenchymal transition in esophageal cancer cells, which enhanced treatment resistance, migratory capacity, and clonogenicity." (PMID 36572816, 2023). "Elevated IL-6 in serum has been shown to be related to disease progression and poor prognosis in esophageal cancer." (PMID 35610567, 2022). "We have recently shown that increased STAT3 activity correlates with chemoradiotherapy resistance in rectal and esophageal cancer cells, and that inhibition of the IL-6/STAT3 pathway results in sensitization to CRT." (PMID 35267609, 2022). "For example, CAFs increase the ratio of FoxP3+ (Tregs) and CD8+ tumor-infiltrating lymphocytes via IL-6 in TME, and IL-6 blockade enhances the immunotherapy efficacy in esophageal cancer models." (PMID 36703971, 2022). "For the transcriptional data for IL-6 in esophageal cancer tissue, the median value was selected as the cutoff point, and the patients were divided into high and low IL-6 expression groups." (PMID 34881181, 2021). "The Cancer Genome Atlas (TCGA) database was used to analyze the correlations between IL-6 and prognosis and between IL-6 and PD-L1 gene expression in esophageal cancer." (PMID 34881181, 2021). "The TCGA esophageal cancer data showed that IL-6 expression was positively correlated with PD-L1 expression and that patients with high IL-6 expression had a significantly lower overall survival rate than patients with low IL-6 expression." (PMID 34881181, 2021). "To determine the role of IL-6 in tumorigenesis of esophageal cancer, we used IL-6 KO mice to generate esophageal cancer that induced by 4NQO." (PMID 34393797, 2021). "IL-6 was reported to positively associate with angiogenesis, EMT, and poor prognosis in esophageal cancer." (PMID 34393797, 2021). "The study determined that CAF suppression of CD8+ and promotion of FoxP3+ tumor-infiltrating lymphocytes was mediated by IL-6, suggesting IL-6 blockade via CAF targeting as a possibility to enhance the efficacy of immunotherapy in esophageal cancers." (PMID 33808627, 2021). "For example, Let-7 affected the sensitivity of cisplatin by IL-6/STAT3 pathway in esophageal cancer." (PMID 34096570, 2021). "In particular, in esophageal carcinoma, binding its receptor (IL-6Rα), IL-6 can induce STAT3 and MEK/ERK signaling pathways, promoting proliferation and invasion of tumor cells." (PMID 34572947, 2021). "The inhibition of IL-6 transcription further potentiated these effects, suggesting that the inhibition of IL-6 transcription was how apigenin exhibited its anticancer effects in esophageal cancer cells." (PMID 32708138, 2020). "We also showed distinct systemic cytokine signatures in gastric and esophageal cancers and their benign conditions, with cytokine panels consisting of IL-1β/IL-1ra/IL-6/RANTES or IL-1β/IL-6/IL-4/IL-13 holding promise as differential biomarkers in GC." (PMID 32630408, 2020). "In the present study, we reported that apigenin inhibited IL-6 transcription and gene expression in esophagus cancer cells." (PMID 31572184, 2019). "We examined the IL-6 gene expression data in human esophagus cancer using a publicly available database from TCGA network derived from the UCSC Xena Browser." (PMID 31572184, 2019). "Taken together, these results indicated that apigenin decreased IL-6 expression through inhibiting the transcription activity of IL-6 in esophagus cancer cells." (PMID 31572184, 2019). "We first evaluated the effect of apigenin on the expression of IL-6 in human esophagus cancer Eca-109 and Kyse-30 cells." (PMID 31572184, 2019). "In esophagus cancer patient samples, the IL-6 mRNA levels in tumor tissues were significantly higher than those in the adjacent normal tissues." (PMID 31572184, 2019). "The results also confirmed that BBR dose-dependently repressed the mRNA expression and secretion of IL-6 in esophageal cancer cells in vitro." (PMID 31950049, 2019).
esophageal cancer (continued). "We further demonstrated that apigenin, a nature flavone product of green plants, inhibited IL-6 transcription and gene expression in human esophagus cancer Eca-109 and Kyse-30 cells." (PMID 31572184, 2019). "Accordingly, we suggested IL-6 is critical in the up-regulation of PD-L1 expression in esophageal cancer." (PMID 26761210, 2016). "Given the positive association between IL-6 and PD-L1 expression in ESCC tumors, we examined the expression of PD-L1 in esophageal cancer cell lines whose IL-6 was regulated." (PMID 26761210, 2016). "Serum IL-6 levels have been shown to be higher in patients with esophageal carcinoma than in healthy controls." (PMID 26761210, 2016). "The correlation between IL-6 levels and tumor progression indicates that IL-6 in tumor tissues plays a pivotal role in the pathological behavior of esophageal carcinoma." (PMID 26761210, 2016). "We therefore investigated the role of IL-6 in esophageal SCC in vitro and in vivo, and examined the correlation between IL-6 levels and clinical outcomes in esophageal cancer patients." (PMID 23561329, 2013). "We retrospectively analyzed the clinical outcomes of 173 patients with esophageal SCC, and examined the correlation between IL-6 levels and clinical outcomes in esophageal cancer patients." (PMID 23561329, 2013). "In cell experiments, the IL-6 silencing vector induced both an increase in E-cadherin levels in esophageal cancer cells, and decreases in MMP-9 levels." (PMID 23561329, 2013). "Colony-forming assay data and the in vivo delay in tumor growth demonstrated that the IL-6 silencing vector significantly sensitized esophageal cancer cells to irradiation." (PMID 23561329, 2013). "Similar to other series, we found that IL-6 and IL-6R were detected in both esophageal cancer specimens and esophageal carcinoma cell lines." (PMID 23561329, 2013). "There was a positive link between IL-6 and tumor stage and disease failure in patients with esophageal cancer." (PMID 23561329, 2013). "Of the 173 esophageal cancer tissues, 88 (51%) showed positive IL-6 immunoreactivity (41% (45/109) in ≤ T3 versus 67% (43/64) in T4, P = 0.001)." (PMID 23561329, 2013). "Elevated serum levels of IL-6 have been shown to be correlated with disease progression and poor prognosis in patients with esophageal cancer." (PMID 22917173, 2012). "In esophageal cancer, the accumulation of inflammation-derived secretory factors, including IL-6, Insulin-like growth factor-binding protein-3 (IGFBP-3), and CXC motif chemokine ligand 16 (CXCL16), results in the upregulation of CD38 in myeloid-derived suppressor cells (MDSCs)." (PMID 40382743, 2025). "The preliminary results from online databases and microarray exploration of esophageal cancer tissues suggest that IL-6 may regulate the tumor microenvironment and contribute to immunosuppression." (PMID 40433391, 2025). "Moreover, we found that radiotherapy downregulates let-7a expression in esophageal cancer cells and that decreased let-7a expression leads to increased Dicer and IL-6 expression, thereby reducing the sensitivity of esophageal cancer cells to radiotherapy." (PMID 38114473, 2023). "Our findings suggest that early changes in serum let-7a and IL-6 levels may be used as a biomarker to predict the response to radiotherapy in patients with esophageal cancer and provide new insights into subsequent treatments." (PMID 38114473, 2023). "Additionally, including IL-1β and IL-6 and TNF-α have been linked also with the pathogenesis of esophageal cancer." (PMID 34830880, 2021). "Furthermore, the correlation between IL-6 and PD-L1 gene expression was evaluated, and a positive correlation was found between PD-L1 and IL-6 expression in esophageal cancer (R=0.34, P<0.01)." (PMID 34881181, 2021). "The inhibitory effect of MSA on esophageal cancer was IL-6 dependent." (PMID 34393797, 2021).
esophageal cancer (continued). "The treatment strategy targeting components of the IL-6/JAK/STAT3 signaling pathway might play a role in optimizing treatment outcomes in esophageal cancer." (PMID 31126307, 2019). "The author found that orally administered CR did not affect the proliferation of esophageal cancer cells but prevented the weight loss of tumor-bearing mice and reduced tumor and serum IL-6 levels." (PMID 31950049, 2019). "IL-6, due to its pro-inflammatory activity, is known to increase the risks of various kinds of cancers in obese patients, such as breast, liver, prostate, colon, and esophagus cancers." (PMID 29141038, 2017). "Also IL-6 seems to play a role in tumor progression and prognosis in patients with carcinoma of the esophagus." (PMID 28537901, 2017). "In addition, the frequency of PD-L1 immunoreactivity was significantly higher in IL-6-positive esophageal cancer specimens." (PMID 26761210, 2016). "We previously reported that IL-6 is a significant predictor for esophageal cancer." (PMID 26761210, 2016). "Furthermore, as demonstrated using migration scratch assays, IL-6 silencing vector attenuated the invasive capacity of esophageal cancer cells." (PMID 23561329, 2013). "When esophageal cancer cells with control vectors and those with IL-6 silencing vectors were subcutaneously implanted into mice, we found that the growth inhibiting effect induced by IL-6 silencing vector associated with lower expression levels of EMT- and angiogenesis-related factor." (PMID 23561329, 2013). "The mean IL-6 levels in serum samples from 71 patients with esophageal cancer were 39 ± 7.7 pg/mL." (PMID 23561329, 2013). "FN1, TNF, and IL-6 may be potential target genes regulated by APE1 in esophageal cancer." (PMID 40330011, 2025). "Additionally, probiotics possess anti-inflammatory properties as they can suppress chronic inflammation, a key factor in the development of esophageal cancer, by reducing the production of pro-inflammatory cytokines such as IL-6 and TNF-a, thus slowing or preventing cancer progression." (PMID 39346897, 2024). "Moreover, the administration of a let-7a mimic and an anti-IL-6 antibody has the potential to modulate the communication between radioresistant and radiosensitive cells and enhance the efficacy of radiotherapy for esophageal cancer." (PMID 38114473, 2023). "We will also collect serum samples from additional esophageal cancer patients on day 7 after radiotherapy initiation and develop models to predict the radiotherapy response based on early changes in the circulating let-7a and IL-6 levels observed during radiotherapy." (PMID 38114473, 2023). "Therefore, we hypothesize that inhibiting IL-6 transcription is a new mechanism by which apigenin exhibits its antitumor activity in esophagus cancer." (PMID 31572184, 2019). "In this study, we analyzed interleukin 6 (IL-6) gene expression in human esophagus cancer patients and showed that IL-6 mRNA levels are significantly higher in tumor tissues and negatively correlated with overall survival, suggesting that IL-6 is a potential therapeutic target for esophagus cancer." (PMID 31572184, 2019). "Therefore, it appears that altered STAT3 activation and subsequent EMT might, at least in part, be responsible for the aggressive tumor behavior in IL-6-positive esophageal cancer." (PMID 23561329, 2013). "The plasma expression levels of IL-32 in patients with malignant esophageal cancer increased, promoting the progression of esophageal cancer through the activation of NF-κB and the increased levels of cytokines TNF-α, IL-6, and IL-1β40." (PMID 38584169, 2024). "LPS induced IL-6 and TGF-β1 secretion in esophageal cancer cell lines, and E-cadherin was significantly decreased after LPS treatment, promoting EMT." (PMID 37511547, 2023). "In accordance with this, stromal IL-6 promotes EMT and, consequently, migration and therapeutic resistance in esophageal carcinoma." (PMID 34572947, 2021).